CD47 (CD47 molecule)
Diseases named in the same sentence as CD47 in open-access papers (continued):
Sharing a sentence is not in itself a finding about the gene and the disease.
tumor (continued). "The CD47/PD‐L1 antibodies combination exhibits durable antitumor immunity but also elicits excessive immune‐related adverse events (IRAEs) caused by the on‐target off‐tumor immunotoxicity, hindering their clinical benefits greatly." (PMID 37132609, 2023). "Resistance to ADCP may also occur through the overexpression on MM cells of CD47, which binds to SIRPα on tumor‐associated macrophages (TAMs) and contributes to the immune escape of tumor cells by inhibiting ADCP." (PMID 37840445, 2023). "Furthermore, CD47 expression is associated with a poor prognosis in various cancers, suggesting its involvement in tumor progression and metastasis." (PMID 38188674, 2023). "This evidence suggested that the antitumor effect was closely associated with downregulation of CD47 expression in tumor cells and could be further promoted, following immune response." (PMID 37063284, 2023). "Simultaneously, the information could provide valuable insights for releasing the tumor immune escape caused by CD47-SIRPα." (PMID 37375166, 2023). "To validate the inhibitory role of CD47 expression in neutrophil-mediated killing of tumor cells, we screened a large number of tumor cell lines and evaluated the expression levels of common tumors associated antigen targets, including CD47, as well as the expression of EGFR, EpCAM, and HER2." (PMID 37444515, 2023). "Tumor heterogeneity is also a challenge of CD47-targeted therapies, as some cancer cells may have varying expression levels of CD47, which can lead to differences in susceptibility to CD47-targeted therapies among different cells." (PMID 38188674, 2023). "We also dissected the underlying molecular mechanisms and revealed that KRAS mutations could directly activate CD47 in cancer cells to inhibit the activity of macrophages, thereby leading to innate immune evasion and aggressive tumor progression." (PMID 36413402, 2023). "Furthermore, CD47 expression on both tumor cells and stromal cells within the TME has been implicated in promoting immune suppression and conferring resistance to the immunotherapy." (PMID 38188674, 2023). "Although the specific mechanism underlying CD47′s contribution to tumor metastasis remains to be defined, these studies suggest that CD47 may also contribute to tumor progression by supporting metastatic dissemination." (PMID 37958404, 2023). "They suggested that a gradual increase in CD47 expression is associated with tumor progression." (PMID 36010209, 2022). "Furthermore, in a syngeneic breast cancer mouse model, co-treatment with Trastuzumab and anti-CD47 mAbs improved tumour control and was associated with macrophage pro-inflammatory polarisation and cytotoxic gene expression in CD8+ T cells." (PMID 35020853, 2022). "Previous studies have also revealed that CD47 inhibition could promote CD8+ T cells for tumor cell killing and loss of CD47 in the tumor stroma increases the sensitivity of some tumors to standard therapy." (PMID 35697717, 2022). "Moreover, GRP78 and CD47 co-expression results in increased tumor macrophage infiltration and is associated with poor prognosis in BC patients." (PMID 36345017, 2022). "Furthermore, targeting CD47 to a particular tumour‐associated antigen carries an inherent risk in often heterogenous cancers." (PMID 35908284, 2022). "RT‐induced CD47 loss reportedly enhances immune‐mediated tumour clearance." (PMID 35261190, 2022). "Moreover, the CD47-SIRPα axis blockade caused enhanced anti-tumor phagocytosis of TAMs, demonstrating their potential as anti-tumor effectors." (PMID 35054787, 2022). "In addition, the correlations between CD47 expression and immune cell infiltration, stromal components, immune checkpoint genes, tumor mutational burden (TMB), and microsatellite instability (MSI) were analyzed from the public database." (PMID 35697717, 2022).
tumor (continued). "Consequently, Those data indicated that the expression level of CD47 was closely linked to the extent of tumor immune infiltration among cancers in both favorable and unfavorable cancers." (PMID 35697717, 2022). "CD47 expression was negatively associated with tumor purity in UCEC (r = − 0.187, P = 0.001)." (PMID 35697717, 2022). "Moreover, we analyze the association of CD47/SIRPα with the PD-L1/PD-1 axis and with parameters related to tumor-infiltrating lymphocytes." (PMID 35406573, 2022). "In addition, we found that CD47 expression was associated with tumorigenesis and tumor progression, suggesting its potential as a prognostic biomarker." (PMID 36010209, 2022). "In addition, high CD47 expression was significantly associated with the presence of ulceration (p = 0.019) and larger tumor size (p = 0.004) in SCC." (PMID 36010209, 2022). "CD47 is associated with drug resistance in tumor-initiating cells." (PMID 34768921, 2021). "We assessed tumor cell characteristics associated with immune suppression (PD-L1, CD47, and HVEM) or known tumor features associated with response/resistance to daratumumab treatment (expression levels of CD38 and the complement inhibitory proteins CD55 and CD59)." (PMID 34070044, 2021). "CD47 was also implicated in other tumor cell defense mechanisms." (PMID 34768921, 2021). "However, IBI-322 is preferentially distributed in PD-L1-positive tumor cells, thus decreasing the possible adverse effects of this target associated with monospecific anti-CD47 antibodies." (PMID 34305918, 2021). "The experimental data accurately reflected the changes of tumor microenvironment caused by the anti-CD47 treatment, thus confirming that anti-CD47 immunotherapy increased the anti-tumor effect of immune cells and reduced the numbers of macrophages related to immunosuppression." (PMID 33648534, 2021). "Furthermore, non-functional SIRPα variant soluble proteins in preclinical models and anti-CD47 mAb in non-Hodgkin’s lymphoma patients have been combined with rituximab, resulting in tumor regression." (PMID 34638388, 2021). "SIRPα (signal regulatory protein α)–CD47: The SIRPα receptor is expressed by tumor-associated macrophages, and binding with the CD47 ligand expressed by tumor cells induces the phosphorylation of SIRPα with a final inhibitory effect on the phagocytosis process." (PMID 34207243, 2021). "Disruption of SIRPα:CD47 signaling also increased NK cell activation and cytotoxicity while CD47 overexpression inhibited cytotoxic killing of tumor or MHC-deficient target cells in vitro; importantly, this latter observation was dependent upon SIRPα expression on NK cells." (PMID 34603322, 2021). "Relative low expression of CD47 in PanNETs was associated with tumor metastasis trends." (PMID 33765961, 2021). "Furthermore, they found increased tumor-associated macrophages and an enhanced effect of anti-CD47 blockade limiting tumor growth in TMEM30A-knockout models." (PMID 33803671, 2021). "As a result, CD47 has been implicated in aiding tumour cell evasion from immune system signals." (PMID 33789677, 2021). "NTP treatment not only reduced tumor size, but also caused a slight reduction in CD47." (PMID 33540720, 2021). "Furthermore, we found that MYC inhibition can decrease Cd47 in tumor-associated macrophages in vitro." (PMID 32685002, 2020). "Interestingly, vaccination with CD47-deficient tumor cells induced a significantly increased expansion and activation of CD11c+SIRPα+ (F4/80−CD64−) DCs, but not of F4/80+CD64+ monocytes/macrophages." (PMID 31996683, 2020). "This anti-tumor activity was like a full genetic deficiency of CD47." (PMID 32677994, 2020). "Indeed, knockout of CDC50A, a subunit of ATP11C that participates in PS flipping, increases tumor-associated macrophages and enhances the effect of anti-CD47 blockade on limiting tumor growth." (PMID 32802188, 2020).
tumor (continued). "Agreed with the reported partial tumor growth inhibition by RT combined with blocking CD4750,53, a similar insufficiency in tumor growth inhibition was observed by RT combined with an antibody blocking either CD47 or HER2 or with CRISPR-mediated gene deficiency." (PMID 32929084, 2020). "Our results indicate that CD47-deficient whole tumor cells can induce antitumor responses." (PMID 31996683, 2020). "Interestingly, biopsies taken from patients have correlated response to CD47 inhibition with a high density of infiltrated tumor-associated macrophages that are abundant in SCLC." (PMID 32751469, 2020). "Our datasuggest that the tumor killing ability of RQ-present co-culture may be linked to the prevention of phagocytosis-inhibition resulting from CD47-SIRPα interaction." (PMID 32020472, 2020). "Other affected genes are related to apoptosis (Ddx20, Ikbip), integrin-associated signal transduccion (Cd47), stress protein with antioxidant-associated tumor suppressive function (Tp53inp1/Trp53inp1), calcium signaling (Stim1), as well as those related to proliferation and survival (Lin28a)." (PMID 30742662, 2019). "In particular, immune recognition-associated proteins with impact on tumor cell clearance through phagocytosis, such as CD47 and calreticulin, could contribute to adaptive resistance and immune escape." (PMID 32082304, 2019). "These immunomodulatory cytokines are also responsible for an increase in the T cell subsets, orchestrating phenotypic shifts in the CD4 T cell subtypes, and play a role in the increasing cytotoxic T cell activity in the tumor microenvironment of CD47 deficient tumors." (PMID 31882679, 2019). "To further understand the mouse immune cell subpopulations associated with anti-tumor response following anti-CD47 treatment, we harvested the tumors on day 15 following the anti-CD47 treatment and analyzed the CD45-positive immune cells by scRNA-seq with 10x Genomics pipeline." (PMID 31771616, 2019). "It indicates that GrA exerts inhibitory effects against pancreatic CSCs associated with CD47 down-regulation, implying that GrA might play a positive role in modulating the interaction between macrophages and tumor cells." (PMID 31139022, 2019). "CD47/CD133 expression was associated with an increased risk of tumor progression in ESCC patients." (PMID 30741466, 2019). "We hypothesized that high density of tumour infiltrating Tregs, and IDO1+ TAMs, as well as high tumour CD47 and IDO1 expression would be associated with adverse outcome." (PMID 31358801, 2019). "The SIRPα-extracellular vesicles-mediated CD47 blockade causes tumor growth inhibition." (PMID 29850495, 2018). "In this context, the elevated expression of CD47 in many cancers could result in enrichment of tumor-associated miRNAs and other noncoding RNAs in CD47+ EVs33." (PMID 29416092, 2018). "Analyses of human tumor tissue have implicated CD47 in cancer." (PMID 30133535, 2018). "Risk for toxicity and anti-tumor effectiveness from a CD47 blockade is still under observation." (PMID 30533489, 2018). "The amalgamation of these results indicates that CD47 deficiency in tumor endothelial cells may promote tumor growth by enhancing their angiogenic potential and tumor vascular integrity and stability." (PMID 27283989, 2017). "It is important to note that targeting tumor cells with CD47-specific blocking antibodies or soluble signal regulatory protein-α (SIRPα) variants inhibits CD47- SIRPα interaction and facilitates tumor cell removal by macrophages, leading to reduction tumor growth and metastasis." (PMID 29348826, 2017). "GBSCC is no exception, as immune surveillance loss could result from the elevated expression levels of CD47 across most of the studied tumours." (PMID 28886030, 2017). "However, addition of TSP1 into the tumor cell culture supernatant from CD47-deficient mice significantly enhanced macrophage recruitment." (PMID 27283989, 2017).
tumor (continued). "The overexpression of CD47 in human NSCLC tumor tissues and cell lines suggest that it might be associated with disease progression." (PMID 27411490, 2016). "Similarly, an engineered SIRPα-variant-presenting cell membrane-coated magnetic nanoparticle was fabricated to reprogram tumor-associated macrophages (TAMs) and inhibit the CD47-SIRPα pathway, resulting in synergistic activation of the macrophage immune response and controlled tumor progression." (PMID 40114728, 2025). "Additionally, CD47 expression by the tumor has been associated with poor prognosis." (PMID 38577107, 2024). "Cox multivariate analysis revealed that CD47 expression and clinical staging are independent risk factors for prognosis, suggesting that reducing CD47 expression could enhance immune response, inhibit tumor cell proliferation, and potentially serve as a specific therapeutic approach for NSCLC." (PMID 39652550, 2024). "However, CAR T cells with constitutive SGRP secretion, given its high affinity to CD47, might risk off-tumor toxicity." (PMID 39521782, 2024). "Indeed, the high expression of CD47 on tumor cells is associated with poor prognosis." (PMID 36768201, 2023). "In addition, blocking the CD47/SIRPα axis can induce M1 polarization in tumor-associated macrophages and increase macrophage recruitment, and can promote phagocytosis by DSs and consequent antigen presentation to CD8+ T-cells, inducing an adaptive anti-tumor immune response." (PMID 37371818, 2023). "Furthermore, inhibition of CD47 normalized tumor vasculature in a multiple myeloma model, which was associated with reduced expression of pro-angiogenic factors, increased expression of anti-angiogenic factors, and tumor growth inhibition." (PMID 37958404, 2023). "Furthermore, hybrid CMNs repolarize tumor‐associated macrophages into the M1 phenotype, blocking the CD47–SIRPα signaling pathway, enhancing macrophage‐mediated phagocytosis of cancer cells, improving T cell immunity against cancer, and reducing systemic‐infusion‐induced side effects." (PMID 37409429, 2023). "An important signal system is the CD47/signal regulatory protein alpha (SIRPα) pathway, which is the target for several inhibitory drugs that are currently being investigated in clinical trials including soluble variants of SIRPα to outcompete macrophage binding to CD47 on the tumor-cells." (PMID 35883493, 2022). "Furthermore, CD47 is overexpressed in tumours where its expression is associated with poor progression-free survival and inversely correlated with macrophage infiltration in tumour tissues loaded on exosomes, thereby promoting tumour immune evasion." (PMID 36298556, 2022). "In addition, the overexpression of the integrin-associated protein (CD47) on the surface of tumor cells, which can send the antiphagocytic “don’t eat me” signal to macrophages and evade phagocytosis, is another crucial factor of tumor invasion." (PMID 35931666, 2022). "Additionally, it was demonstrated that CD47-encoding E. coli organisms could stimulate systemic tumor antigen-specific immune responses, induce durable tumor regression, and lead to long-term survival in a syngeneic tumor model." (PMID 34138211, 2021). "According to dichotomous analysis with clincopathologic factors, high CD47 expression has a significant association with the pN stage as well as lymphatic invasion, which suggests that the permeability of the tumor may result in more frequent positive CD47 expression in AJCC stage III." (PMID 33917794, 2021). "CD47 × CD19 or CD20 bispecific antibodies are able to improve tumor lysis by effector cells in a targeted fashion by selectively blocking the CD47-SIRPα interaction on malignant cells expressing a specific tumor-associated antigen, thus improving efficacy and minimizing toxicity." (PMID 35582375, 2021).
tumor (continued). "Promisingly, the delivery of encoded nanobody antagonist of CD47 by tumor-colonizing bacteria increases activation of tumor infiltrating T cells, stimulates rapid tumor regression, prevents metastasis, and leads to long-term survival in a syngeneic tumor model." (PMID 33436010, 2021). "Thus, we propose that injection of CD47-deficient tumor cells or cells carrying tumor antigens (TAs) may induce strong antitumor immunity." (PMID 31996683, 2020). "Increasing T cell priming is hypothesized to underlie the success of CD47 blockade in tumor models." (PMID 32477354, 2020). "However, the CD47 expression pattern in tumor-infiltrating lymphocytes (TILs), which are associated with prolonged overall survival and serve as a positive prognostic factor, is largely unknown." (PMID 32811852, 2020). "In summary, the ionophore antibiotic GrA shows significant potential in suppressing pancreatic CSCs in association with CD47 down-regulation and re-distribution, implying that GrA might play a positive role in modulating the interaction between macrophages and tumor cells." (PMID 31139022, 2019). "Indeed, a variant of CD47 with improved affinity for SIRPα had a synergistic effect when used in combination with tumor-specific monoclonal Abs to ameliorate phagocytosis of tumor cells in vitro, although its antitumoral effects in vivo have not been evaluated." (PMID 31921125, 2019). "Furthermore, tumour cell-bound CD47 is implicated in this process." (PMID 30850588, 2019). "Thus, the enhanced VEGF-VEGFR2 signaling may contribute to the observed enhancement of tumor angiogenesis in CD47-deficient mice." (PMID 27283989, 2017). "The tridecapeptide PSFL‐NK13, specifically designed to target this complex, significantly reduced the surface expression of both CD47 and αvβ3 in tumor cells." (PMID 41168993, 2026). "Meanwhile, the ectopically expressed SIRPαECD competitively bound to CD47 on tumor cells, thereby blocking the endogenous SIRPα-SHP2 interaction in a dominant-negative manner." (PMID 42192422, 2026). "OVV-αCD47nb maintained infectivity and secreted anti-CD47 nanobodies that enhanced macrophage phagocytosis of tumor cells." (PMID 41858619, 2026). "Early clinical trials are testing dual-target and logic-gated CAR-M designs, like HER2/CD47 constructs, offering a promising path toward greater specificity and sustained tumour control." (PMID 41559435, 2026). "This reduction weakened the CD47–SIRPα axis signaling, enhanced macrophage‐mediated phagocytosis of cancer cells, and significantly suppressed tumor growth." (PMID 41168993, 2026). "Recent studies revealed that SIRPA deficiency reprogrammed tumor-associated macrophages toward an antitumor phenotype, and SIRPA functioned independently of CD47." (PMID 42116089, 2026). "CD47 is mainly localized on the cell membranes and within the cytoplasm of tumor cells, and in some immune cells." (PMID 40926176, 2026). "In vivo, GV1001 significantly inhibited tumor growth, suppressed CD47 expression, increased macrophage infiltration, and induced tumor cell necrosis and apoptosis in both murine OSCC syngeneic graft model and human OSCC xenograft model." (PMID 41977514, 2026). "Given the critical role of the CD47–SIRPα axis in protecting tumor cells from macrophage-mediated phagocytosis, we sought to systematically identify tumor-intrinsic genetic regulators of CD47 expression." (PMID 41601654, 2026). "In cancer, QPCTL is a promising immunotherapy target since QPCTL-mediated CD47 pyroglutamylation prevents macrophages from phagocytosing tumor cells." (PMID 41988205, 2026). "An anti-PD1 immune checkpoint inhibitor in a CD47-null tumor background led to complete tumor regression confirming a key role for CD47 in tumor immunity." (PMID 41701713, 2026). "We found that CD47 was significantly up-regulated in drug-resistant cells, which further demonstrated that the up-regulation of CD47 helped tumour cells escape phagocytosis by macrophages." (PMID 41438583, 2026).